PF4 (platelet factor 4)
Diseases named in the same sentence as PF4 in open-access papers (continued):
Sharing a sentence is not in itself a finding about the gene and the disease.
tumor (continued). "These Cd41+ tumor cells showed strong staining for cleaved Caspase-3 in tumors from Pf4-Cre mice; however, cleaved caspase-3 in Cd41+ tumor cells was significantly reduced in tumors from Dicer1fl/fl/Pf4-Cre mice." (PMID 34936674, 2021). "Cytokines produced by systemic inflammatory reaction can also increase the number of platelets, release platelet-derived growth factor, platelet-reactive protein and platelet factor-4, which promote tumor proliferation, invasion and angiogenesis." (PMID 34893056, 2021). "Platelet counts were unaltered at d16, but by d21 of ectopic tumor growth, platelet counts were significantly decreased, but again to similar degrees in both control and Dicer1fl/fl/Pf4-Cre mice." (PMID 34936674, 2021). "Densitometry analysis showed that five cytokines, IL-4, AXL, IL-1β, IL-9, Exotaxine-2 and IL2, were upregulated, and two cytokines, PF4 and IL-6, were downregulated in the tumor environment of JEG3-Sh-NLRP7 cells." (PMID 34203890, 2021). "In contrast, lymphocytes were unexpectedly reduced in the Dicer1fl/fl/Pf4-Cre mice compared to controls at d21 of tumor growth." (PMID 34936674, 2021). "This subpopulation differentially expresses genes that have been shown to be tissue-reparative (Hmox1, Gas6) and tumor-promoting (Pf4, Fgfr1, and Nrp2)." (PMID 33072601, 2020). "This study highlights PF4 as a promising candidate early disease biomarker, potentially detectable in patients harbouring tumours which would likely go undetected with current imaging modalities." (PMID 31722230, 2020). "CXCL4, alternatively known as platelet factor 4, was found to be upregulated in various tumoral tissue." (PMID 33489879, 2020). "To mimic the local increase of PF4 concentration due to either platelet activation or a bolus injection of rPF4, we simulated a situation of controlled release of PF4 in the tumor interstitium." (PMID 31379588, 2019). "Together, these results indicate that HSPG promotes angiogenesis in tumor tissue, and the secretion of PF4 counteracts the pro-angiogenic effect of HSPG." (PMID 31379588, 2019). "With the baseline secretion rates, the model predicts that the pro-angiogenic factors (VEGF and FGF2) and anti-angiogenic factors (TSP1 and PF4) have significantly different distribution patterns in tumor tissue." (PMID 31379588, 2019). "To summarize, we simulated relevant tumor scenarios in which the PF4 concentration would suddenly increase, such as following platelet activation or administration of exogenous PF4 as an anti-angiogenic treatment strategy." (PMID 31379588, 2019). "Physical interaction between PF4 and VEGF provided a molecular mechanism for the tumor suppressive activity of PF4." (PMID 31043929, 2019). "PF4 is down regulated in newly diagnosed MM patients and has great potential of tumour-suppressive function in MM development." (PMID 31043929, 2019). "When this effect is stronger than the sequestration that occurs when PF4 binds directly to pro-angiogenic factors, the level of unbound VEGF and FGF2 will be higher compared to the tumor microenvironmental condition with lower PF4 secretion (Column I)." (PMID 31379588, 2019). "To explain these results, we further investigate how cHSPG level and PF4 secretion modulate the signaling complexes for each of the angiogenic factors modeled in the tumor tissue." (PMID 31379588, 2019). "Column I, the model predicts that increasing cHSPG increases the angiogenic ratio (the tumor tissue is shifting to a more pro-angiogenic state) and increasing PF4 decreases the angiogenic ratio (shifting the tumor tissue to a less pro-angiogenic state)." (PMID 31379588, 2019). "Since PF4 mainly influences the other angiogenic factors by competing for the heparan sulfate binding sites, we investigated how the cHSPG level, a tumor-specific property, also affects the outcome of changing PF4 secretion." (PMID 31379588, 2019).
tumor (continued). "Platelets are associated with poor cancer prognosis because they induce the platelet-derived growth factor, vascular endothelial growth factor, and platelet factor 4, which can lead to tumor cell proliferation or invasion into other cells." (PMID 30285668, 2018). "There were two underlying mechanisms: decreased blood vessel integrity in the premetastatic lungs and increased production of hematopoietic stem/progenitor cells (HSCs) and myeloid derived suppressor cells (MDSCs) in tumor-bearing PF4 KO mice." (PMID 27223426, 2017). "Bone marrow cells from wild type and PF4 KO B16F10 tumor-bearing mice were stained with HSC markers Sca1 and CD117, as well as a HSC negative marker Lin." (PMID 27223426, 2017). "Consistently, under tumor conditions, there was more dye in the PF4 KO lungs than that of the WT lungs." (PMID 27223426, 2017). "Together, these data demonstrate that PF4 derived from myeloid cells inhibited tumor cell metastasis." (PMID 27223426, 2017). "There was a significantly higher percentage of Gr-1+CD11b+ cells in the bone marrow, spleen, peripheral blood as well as lung of normal or tumor-bearing PF4 KO mice, than those from the WT mice." (PMID 27223426, 2017). "In this regard, lyso-phosphatidic acid (LPA) and platelet factor 4 (PF4) are also released from activated platelets and been shown to positively enhance tumour growth." (PMID 28737696, 2017). "Our data from PF4 KO mice studies showed a decreased metastasis phenotype are strong and perhaps raise awareness and cautions to the data suggesting pro-tumor function of PF4." (PMID 27223426, 2017). "In cancer patients, PF4 expression levels were negatively correlated with tumor stage and positively correlated with patient survival." (PMID 27223426, 2017). "There were a higher percentage of CD31+ cells in the CD45-Lin- population in the lungs of PF4 KO mice compared to the WT mice when mice with similar tumor size were analyzed." (PMID 27223426, 2017). "Podoplanin expressed by some tumor cells, tissue factor and platelet factor 4(PF4) can be the platelet activation markers at the same time." (PMID 29383198, 2017). "To examine the blood vessels, we used the B16F10 tumor-bearing PF4 KO mice compared to the WT control on day 18 after tumor cell injection, which is considered as the premetastatic phase for B16F10 model." (PMID 27223426, 2017). "In summary, our studies demonstrate that PF4 is a critical anti-tumor factor in the premetastatic site." (PMID 27223426, 2017). "Our finding of PF4 function in the tumor host provides new insight to the mechanistic understanding of tumor metastasis." (PMID 27223426, 2017). "PF4 deletion significantly increased tumor metastasis suggesting PF4 is a critical anti-tumor factor in the premetastatic site." (PMID 27223426, 2017). "Such platelets can express elevated levels of platelet-derived growth factor, vascular endothelial growth factor, and platelet factor 4, which can stimulate tumor cell proliferation and adhesion to other cells and lead to tumor growth and metastasis." (PMID 28489884, 2017). "To evaluate PF4 function in the premetastatic lung, we first did intradermal injection to establish the primary tumor and premetastatic lung." (PMID 27223426, 2017). "Consistent with the 4T1 model, PF4 expression decreased in both Ly6G+CD11b+ and Ly6C+CD11b+ subsets at later stage (25 days after tumor injection)." (PMID 27223426, 2017). "To investigate PF4 function specifically in Gr-1+CD11b+ cells and to exclude the primary tumor effects on metastasis, we co-injected B16F10 cells with sorted Gr-1+CD11b+ cells from lungs of wild type or PF4 KO mice 14 days after B16F10 tumor injection." (PMID 27223426, 2017). "Our data suggest that premetastatic environment is likely very dynamic, not only there are many pro-tumor factors, but also anti-tumor factors such as PF4 reported here." (PMID 27223426, 2017).
tumor (continued). "Recent studies have shown that PF4 was correlated with angiogenesis and immune responses and was a marker of early tumor growth in different tumor types." (PMID 27631372, 2016). "The model is supported by the observation that the levels of PF-4, a tumor angiogenesis inhibitor are decreased with tumor progression." (PMID 27935954, 2016). "Effectively, a simultaneous inhibition of both angiogenesis and tumor growth can be achieved by compounds that mask HSPGs to AGFs: recombinant PF-4 inhibits at once angiogenesis, tumor growth and metastasization." (PMID 25867824, 2015). "We next examined the level of bFGF, PF-4, G-CSF and GM-CSF in tumor extracellular fluid in different dose groups to verify the results." (PMID 25749075, 2015). "We found regulation of angiogenic factors – bFGF and PF4, and chemotactic factors – GM-CSF and G-CSF within tumor microenvironment by SH led to remarkable changes in tumor vasculature and immune status." (PMID 25749075, 2015). "Specifically it has been shown that changes in major platelet antiangiogenic factors such as platelet-associated PF-4 and TSP-1 are upregulated in platelets of tumor-bearing mice." (PMID 24788652, 2014). "PF4 and CTAP-III are two platelet-associated chemokines that modulate tumor angiogenesis, inflammation within the tumor microenvironment, and tumor growth." (PMID 25317080, 2014). "Several studies have shown that PF4 can inhibit tumor growth through its antiangiogenic and immune stimulatory properties, and the slight regression from wtPF4 treatments is in agreement with other antiangiogenic treatments." (PMID 24369443, 2013). "Here, we review the role of PF-4 and CTAP-III in the regulation of tumor angiogenesis; the results of clinical trial using recombinant PF-4 (rPF-4); and the use of PF-4 and CTAP-III as cancer biomarkers." (PMID 23800319, 2013). "Platelet levels of PF-4 as determined by surface-enhanced laser desorption/ionization time-of-flight MS (SELDI TOF MS) are up-regulated following implantation of human tumor xenografts in mice but fall in tumor progression." (PMID 23800319, 2013). "Proteomic studies using surface-enhanced laser desorption/ionization time-of-flight mass spectrometry (SELDI-ToF MS) revealed that platelet factor-4 (PF-4) was upregulated in platelets of tumor-bearing mice." (PMID 22778956, 2012). "Lipocalin 2 (Lcn2) was increased in all models but to a higher level in tumor-bearing mice, while platelet factor 4 (Pf4) was decreased in subacute inflammation but increased in chronic inflammation and cancer." (PMID 21589862, 2011). "PF4 suppresses tumor angiogenesis by attenuating VEGF production and causing the impaired migration of EPCs to the tumor site." (PMID 21693026, 2011). "Platelet factor 4 (PF4) is a potent angiostatic cytokine that inhibits angiogenesis and tumor growth in several animal models." (PMID 21693026, 2011). "PF4 is known to inhibit angiogenesis and tumor growth, but whether inhibitory PF4 binds to site 2 remains unclear." (PMID 41226302, 2025). "Beyond these contacts, platelets discharge a suite of growth-promoting cytokines and chemokines, such as tumor growth factor-β (TGF-β), vascular endothelial growth factor (VEGF), platelet-derived growth factor (PDGF), and platelet factor 4 (PF4) that further fuel tumor expansion." (PMID 40514754, 2025). "For example, drugs that normalize the spatial organization of VEGF and PF-4 in platelet α-granules could potentially inhibit tumor angiogenesis and metastasis." (PMID 38910248, 2024). "In addition, PF4 plays an important role in antiangiogenesis, atherosclerosis, the inflammatory response, and tumor biology mainly through its ability to regulate angiogenesis and the function of different immune cell types." (PMID 36926331, 2023).
tumor (continued). "Among them, in the in vivo model of BRCA, upregulating PF4 can increase the expression of proapoptotic protein and downregulate the expression of antiapoptotic protein, thereby promoting cell apoptosis and achieving the effect of reducing tumor volume." (PMID 35498539, 2022). "Platelets are able to maintain the integrity of tumor vascular endothelium and prevent intra-tumor hemorrhage by secreting granule contents such as 5-hydroxytryptamine (5-HT), platelet factor IV (PF-4), and transforming growth factor (TGF)-β or by directly adhering to damaged blood vessels." (PMID 35799611, 2022). "Although the DC-STAMP, PF4, and PPBP had links with tumor-associated immune response, the mechanisms of the synergistic effects of their interaction remain unclear." (PMID 35571050, 2022). "Likewise, platelets widely interact with tumor cells, whilst they have significant role in inflammation by releasing numerous inflammatory mediators, such as PF4 (CXCL4), P-selectin, and CD40L." (PMID 35439998, 2022). "Platelets secrete platelet-derived growth factor, vascular endothelial growth factor, platelet factor 4, and transforming growth factor-β to increase angiogenesis, microvascular invasion, and cancer cell extravasation to promote tumour progression and metastasis." (PMID 36078877, 2022). "The effect of SH on tumor vessels is due to its ability to restore the balance between pro-angiogenic factor (bFGF) and anti-angiogenic factor (PF4), which may have a great impact on the tumor microenvironment." (PMID 34284780, 2021). "This trend of accelerated tumor growth against a background of miRNA-depleted host platelets continued over the experimental time frame, resulting in an overall 1.54 ± 0.07-fold mean daily increase in tumor volume from the Dicer1fl/fl/Pf4-Cre mice compared with control mice." (PMID 34936674, 2021). "However, tumor mass was significantly increased by 1.50 ± 0.13-fold at d21 from the Dicer1fl/fl/Pf4-Cre mice compared with control mice, reflecting similar increases in tumor volumes." (PMID 34936674, 2021). "Additionally, in the tumor niche it is possible that CX3CL1 increases the production of platelet-derived factor 4 (PF-4)/CXCL4 in macrophages." (PMID 32466280, 2020). "Platelets may secrete cellular growth factors such as platelet-derived growth factor, VEGF, transforming growth factor beta, and platelet factor 4, thereby stimulating tumor angiogenesis and growth." (PMID 32122320, 2020). "Therefore, at certain HSPG levels, the secretion of PF4 can enhance the VEGF pro-angiogenic signaling in tumor tissue." (PMID 31379588, 2019). "Thus, the administration of rPF4 as a therapeutic agent will greatly increase the total PF4 level in the tumor." (PMID 31379588, 2019). "Besides the release of endogenous PF4 from platelets, recombinant PF4 (rPF4) has been studied as an anti-tumor therapeutic to prevent angiogenesis, showing efficacy in both in vitro and in vivo settings." (PMID 31379588, 2019). "We found that, depending on the HSPG level, the secreted PF4 can displace more pro-angiogenic factors from the HS binding sites than the amount being sequestered, which eventually increases the level of unbound pro-angiogenic factors in the tumor interstitium." (PMID 31379588, 2019). "Therefore, incorporating FGF2 and PF4 provides a more complete view of the angiogenic interaction network and a more comprehensive understanding of tumor angiogenic state, as compared to previous models." (PMID 31379588, 2019). "The major sources of PF4 based on established studies are likely from tumor cells and platelets." (PMID 31215484, 2019). "Given the fact that platelets are attracted to and accumulate at tumor sites, it is possible that even higher concentrations of PF4 may be present in the local tumor microenvironment when platelet activation occurs." (PMID 31379588, 2019).
tumor (continued). "Our study leverages data from plasma RNA and CTCs, published studies and focused data mining, to propose a testable model in which high concentration of PF4 induces platelet attraction into the tumor microenvironment and regulates expression and/or availability of CLU, CCL5, TGFB1, SRGN and SPARC." (PMID 31215484, 2019). "However, CXCL4L1/PF-4var, later isolated from thrombin-stimulated platelets and differing from CXCL4/PF-4 in three carboxy-terminal amino acids, shows higher anti-angiogenic activity and stronger ability to inhibit tumor growth than CXCL4/PF-4." (PMID 30591657, 2018). "The PF4 KO lungs from tumor-bearing mice showed greater Evans Blue leakage into the lung parenchyma (d vs. c), and greater blood vessel leakage (h vs. g) compared to the lungs from WT tumor-bearing mice." (PMID 27223426, 2017). "Our studies suggest that PF4 is a critical anti-tumor factor in the premetastatic site." (PMID 27223426, 2017). "More specifically, platelets release angiogenic and putative tumour growth factors such as platelet factor 4 (PF4), transforming growth factor beta (TGF-β) and platelet-derived growth factor (PDGF), all of which promote cancer progression and endotelial cell growth." (PMID 28473700, 2017). "Platelets could secrete cellular growth factors (i.e., platelet-derived growth factor, vascular endothelial growth factor, transforming growth factor beta, platelet factor 4, and inflammatory mediators) and then stimulate tumor angiogenesis and growth." (PMID 28539688, 2017). "First, platelets could secrete cellular growth factors including platelet-derived growth factor, vascular endothelial growth factor, transforming growth factor beta, and platelet factor 4, which could stimulate tumor angiogenesis and growth." (PMID 29082257, 2017). "In addition, the anti-tumor effect of PF4 is likely mediated through the CXCR3B receptor, one of the two primary CXCR3 receptors, CXCR3A and CXCR3B." (PMID 27223426, 2017). "On day 28 after tumor injection, there was very minimum level of PF4." (PMID 27223426, 2017). "It is unclear whether the higher PF4 production in B16F10 model contributed to lower metastasis in this model when compared to the higher metastasis in the 4T1 tumor model." (PMID 27223426, 2017). "The up-regulation of CXCL4/PF-4 in these tumor types may be a way to counterbalance angiogenic growth factors." (PMID 25298751, 2014). "PF4 has antiangiogenic effects that can inhibit tumor growth; therefore, a tumor-targeted PF4 (ttPF4) pDNA was constructed to test whether the VNTANST sequence can improve the efficacy of this antiangiogenic therapy." (PMID 24369443, 2013). "Platelet factor 4 (PF-4/CXCL4) and Connective tissue activating peptide III (CTAP-III) are two platelet-associated chemokines that modulate tumor angiogenesis, inflammation within the tumor microenvironment, and in turn tumor growth." (PMID 23800319, 2013). "In addition to its function in thrombosis and hemostasis, PF-4 plays an important role in wound healing, atherosclerosis and tumor biology mainly through its ability to regulate angiogenesis and function of different immune cell types." (PMID 23800319, 2013). "Targeting PF4, another cytokine which has shown some promise in anticancer therapies, was also attempted in the 4T1 tumor model; however, only the wtPF4 was able to inhibit primary tumor growth, although only slightly." (PMID 24369443, 2013). "Previously, it has been reported that PF-4 is a suppressor of angiogenesis and tumor growth." (PMID 22778956, 2012). "Interestingly treatment with PF4-DLR and an anti-ILK1 short interfering RNA is associated with a decrease in tumor mass and a reduction in the number of tumor vessels." (PMID 21060779, 2010).